IL10 (interleukin 10)
Diseases named in the same sentence as IL10 in open-access papers (continued):
Sharing a sentence is not in itself a finding about the gene and the disease.
Anxiety (continued). "Higher IL-10 levels were present in SCZ patients with more severe depressive and anxiety symptoms, and higher IL-10 levels were also associated with lower global functioning (GAF scale), as well as impaired (slower) performance on psychomotor tests." (PMID 41007867, 2025). "In the present study, we found small but significant (p = 0.001) predictive effects of serum TNF-α and IL-10 levels on fear- and anxiety-related personality traits, moderated by age." (PMID 40867746, 2025). "Anxiety was positively associated with higher BCS, creatinine, and IL-10, and negatively associated with IL-1β." (PMID 41268300, 2025). "Experimental studies in rodents support this modulatory role: IL-10 attenuates the inflammation-induced behavioral changes, including anxiety-like responses, while IL-10 knockouts display hyperanxious behaviors." (PMID 40867746, 2025). "An animal study found that acupuncture can inhibit TNF-α and promote the expression of IL-10 in the amygdala to improve the anxiety symptoms of patients with PD." (PMID 39588511, 2024). "The antidepressant and anti-anxiety drug duloxetine was included, which, in addition, by increasing the secretion of interleukin 10 (IL-10), has the potential to reduce the body’s inflammatory process." (PMID 39267763, 2024). "Further research is required to unravel the exact mechanisms of IL-10-mediated anxiety symptom attenuation in GAD patients." (PMID 38902708, 2024). "Chronic stress was found to decrease levels of IL-10 in rat models, and IL-10 as well as IL-4 levels were decreased in medical students who exhibited high anxiety the day before an examination." (PMID 36960908, 2023). "EPM classification reveals that higher anxiety-like behavior is associated with chronic neuroinflammation as Sus-EPM rats have high levels of both IL-6 and IL-10 in PFC." (PMID 37064304, 2023). "IL-10 is also a neuromodulator that reduces anxiety-like behaviors in mice by inhibiting the release of GABA, consistent with our findings in which an increase in GABA secretion was observed in the noise group." (PMID 37623873, 2023). "Susceptible-EPM rats have elevated levels of IL-6 (p = 0.0158) and IL-10 (p = 0.0352) in the PFC suggesting that higher anxiety is associated with chronic neuroinflammation." (PMID 37064304, 2023). "One of the studies showed the relationship between anxiety and IL-10 and a positive relationship in female soccer players with PMS post-game in the luteal phase." (PMID 35873799, 2022). "As in our study, IL-10 was positively correlated with craving for METH while negatively correlated with anxiety measured by GAD-7." (PMID 34869080, 2021). "For instance, significantly lower levels of stimulated IL-4 and IL-10 were witnessed in high-anxiety students measured one day before an academic examination, while a videotaped speech task stressor did not affect IL-4 levels." (PMID 31226144, 2019). "The severity of widespread pain is best predicted by quality of sleep, perceived stress, anxiety, and the three cytokines, while severity of FM is best predicted by stress, anxiety, and IL-10." (PMID 31470635, 2019). "A recent study provides evidence of high levels of IFN-γ and TNF-α but low IL-10 serum levels in anxiety patients when compared to healthy control subjects." (PMID 29181395, 2017). "One trial in experimental autoimmune encephalitis in a rat model of multiple sclerosis showed that gene treatment with IL-10 diminished anxiety and depression symptoms, indicated by voluntary wheel running frequency." (PMID 29181395, 2017). "Basal CRP, IL-6 andTNF-α, as well as most individual LPS-stimulated inflammation markers (IL-6,IL-8, IL-10, IL-18, MCP-1, MIP-1α, MIP-1β, MMP2 and TNF-β) weresignificantly associated with depressive and anxiety symptom severity." (PMID 27244234, 2016). "Next, INF-γ: IL-10 ratio was calculated and then compared between high and low stress/anxiety groups." (PMID 25144199, 2014).
Anxiety (continued). "Consistent with our increased INF-γ and decreased IL-10 data in major stress/anxiety groups the ratio displayed significantly increases in high perceived stress(t = 4.606; p = 0.000)(Figure." (PMID 25144199, 2014). "Consistently, we observed a higher IFN-γ/IL-10 ratio, indicating a shift toward a Th2 response, in high stress/anxiety group." (PMID 25144199, 2014). "Rodents with IL-10 over expression display less anxiety-like behavior, while IL-10 knockouts display a greater depression-like behavior in a forced swim test." (PMID 25002839, 2014). "Mice have been genetically engineered to over-express IL-10 display less anxiety, while IL-10 knock outs display greater levels of anxiety and depressive behavior on a forced swim test, although the impact of IL-10 is more pronounced in females." (PMID 22912626, 2012). "In the human literature, under stressful conditions, those persons with higher levels of IL-10 report less anxiety." (PMID 22912626, 2012). "Maternal anxiety and alcohol exposure reduce microbial diversity and beneficial Bifidobacterium, potentially affecting neurodevelopment through IL-6/IL-10 pathways." (PMID 41450934, 2025). "Additionally, exercise promotes the secretion of anti-inflammatory factors, such as IL-10, which further alleviates inflammation-induced anxiety." (PMID 41144483, 2025). "Increased neuroinflammatory markers such as interleukin-10 (IL-10) in the hippocampus and ionized calcium binding adaptor molecule 1 (IBA1) in the anterior cingulate are associated with anxiety-like behaviors in 5xFAD mice, which are further exacerbated by early-life stress." (PMID 39703925, 2024). "A similar mechanism might be involved in IL-10-mediated anxiety symptom improvement in GAD patients." (PMID 38902708, 2024). "Besides, elevated levels of IL-10 were shown to attenuate anxiety-like behaviors by modulating GABAergic neurotransmission in the amygdala." (PMID 38902708, 2024). "Moreover, administration of IL-10 into rats attenuated the pro-inflammatory cytokine IL-1β-induced anxiety-like symptoms in male rats, demonstrating that IL-10 possesses anxiolytic activities." (PMID 38902708, 2024). "Rats with high anxiety-like behavior had elevated IL-6 and IL-10 mPFC levels." (PMID 37064304, 2023). "In addition, IL-10 has an anti-inflammatory immune function and has effects on the brain and behavior, taking part in anxiety, modulation of mood, and depression symptoms." (PMID 35873799, 2022). "Comparisons to psychosocial measures of anxiety reflected a significant negative association between TNF-α/IL-10 ratio and Preparation for Labor (p = 0.03) and for Relationship with Spouse/Partner (p = 0.01) in pregnancy for the control group." (PMID 34360332, 2021). "Current data is the first to our knowledge, to report IL-10 maladaptation already present in adolescents exposed to childhood maltreatment and/or having high anxiety proneness, in the absence of other apparent causative factors or pathology." (PMID 32298279, 2020). "On the other hand, previous studies found a high dose of IL-10 may induce anxiety in the OFT, two other behavioral tests for anxiety detection." (PMID 32714875, 2020). "Moreover, on both measures of anxiety (time in inner zone and entries into inner zone), Il10-/- AIA mice were impaired for longer than WT-AIA mice." (PMID 37220589, 2016). "Since a close correlation between psychological stress and emotional reaction of anxiety was established in our previous data, the correlation between IL-10 and anxiety may be existence." (PMID 25144199, 2014). "ROC analysis also demonstrated the good predictive value of IL-10 serum measurement in discriminating diseased patients from HCs, suggesting that IL-10 serum level might be a potential biomarker for diagnosis, anti-anxiety drug response monitoring, or disease progression monitoring." (PMID 38902708, 2024). "Interestingly, the presence of anxiety symptoms seemed to influence IL-10 concentrations." (PMID 39200282, 2024).
Anxiety (continued). "At the end of the 12-week experiment, anxiety-like behavior was evaluated by the light/dark box test; compulsive-like behavior by Marble burying, transcriptional regulation of genes Lrrk2, Tlr4, Nfat, Drd1, Drd2, Il6, Il1β, Il10, and iNOS by RT-qPCR; and inflammatory markers by flow cytometry." (PMID 37063320, 2023). "Certainly, any of the psychosocial dimensions of anxiety can develop into chronic stress if not addressed; Preparation for Labor and Relationship with Spouse/Partner were of particular interest due to their association with IL-6/IL-10 and TNF-α/IL-10 ratios." (PMID 34360332, 2021). "Similarly, the IL-6/IL-10 ratio reflected a negative association with anxiety related to Relationship with Spouse/Partner (p < 0.01)." (PMID 34360332, 2021). "After adjusting for the confounding variables, sex, and location of the data collection, anxiety-related behaviors were positively predicted by higher BCS, creatinine, and IL-10, and negatively predicted by IL-1β." (PMID 41268300, 2025). "The results show a significant correlation between anxiety behavioral indicators and CORT levels, inflammatory factors (IL-6, IL-1β, CD86, TNF-α, TGF-β, IL-10), 5-HT, and GABA." (PMID 40078708, 2025). "The anti-inflammatory cytokine IL-10 has been shown to reverse abnormal GABA transmission in the amygdala, mitigating anxiety-like behaviors and substance dependence." (PMID 40507852, 2025). "In males, ZEM12.5 decreased anhedonia- and anxiety-like behavior, decreased cortical and hippocampal PDE4B, and increased plasma interleukin-10." (PMID 40643548, 2025). "The observed reduction in IL-10 levels in GAD patients in our study suggests a potential immunoregulatory imbalance in GAD, with IL-10 playing a role in modulating anxiety severity." (PMID 38902708, 2024). "The anti-inflammatory factor IL-10 reverses abnormal gamma-aminobutyric acid (GABA) transmission in the amygdala, anxiety-like behavior, and substance dependence." (PMID 36624089, 2023). "In addition, L. plantarum DR7 supplementation reduced symptoms of stress, anxiety, and total psychological scores as well as lowering plasma cortisol and pro-inflammatory cytokine levels (interferon-γ and transforming growth factor-α) and increasing anti-inflammatory cytokines levels, such as IL-10." (PMID 36364881, 2022). "Unlike basal inflammation, LPS-stimulated inflammation was stillassociated with (anxiety) symptom severity after adjustment for lifestyle and health(IDS: IL-8, MCP-1, MMP2; BAI: LPS index, IL-6, IL-8, IL-10, IL-18, MCP-1, MMP2,TNF-β)." (PMID 27244234, 2016). "In the present study, the proinflammatory cytokines IL‐6 and TNF‐α affected both emotions and anxiety, but unlike the anti‐inflammatory cytokines IL‐10 and ADPN, they were not related to physical disease severity." (PMID 40700022, 2025). "The elevation of these cytokines (especially IL-1β, IL-6, IL-10, IFN-γ, and TNF-α) may have a role in stress and anxiety in infected patients." (PMID 39935742, 2024). "In P301S mice with anxiety-like phenotypes, inflammation markers appear to differ between sexes: males express more monokines induced by interferon gamma (MIG), TNF-α, IL-13, and IL-10 than females." (PMID 39703925, 2024). "In the absence of anxiety, IL-10 levels were practically identical in both presentations (1.74 ± 2.34 pg/mL) and were considerably higher in the presence of anxiety, especially in the ADHD-AD presentation (4.1 ± 3.71 pg/mL)." (PMID 39200282, 2024). "At the end of the study, HFFD resulted in anxiety‐like behavior, reduced locomotor activity, neuroinflammation (increased brain GFAP, IL‐6, MCP‐1, IFN‐γ, TNF‐α), and systemic inflammation (increased plasma GFAP, IFN‐γ, TNF‐α, IL‐12p70, reduced plasma IL‐10)." (PMID 39619979, 2024). "Alteration of the periphery immune system could affect CNS immune system and induce anxiety‐like behavior, therefore we further measured the levels of IL‐1β, TNF‐α, and IL‐10 in the hippocampus." (PMID 37157948, 2023).
Anxiety (continued). "Regarding the relationships between clinical measurements and systemic inflammation, we found the severity of anxiety evaluated by GAD-7 showing a negative correlation with IL-10 (r = -0.4667, FDR q = 0.0472)." (PMID 34869080, 2021). "Interestingly, the behavioral profile of Il10-/- mice revealed a significantly longer time post-AIA for activity and anxiety-related behaviors to recover." (PMID 37220589, 2016). "Not surprisingly, IL-10 level was much lower in low state anxiety group (t = 5.821, p = 0.000) and low trait anxiety group (t = 6.238, p = 0.000), as compared with the higher counterpart." (PMID 25144199, 2014). "Among all the variables assessed, high circulating IL-10 levels was the only variable strongly associated with high stress/anxiety score, low IFN-γ levels was also observed in high stress/anxiety group, however the statistical differences was not significant." (PMID 25144199, 2014). "Since overall biological function is ultimately influenced by relative proportions of counteracting factors, we also examined the effects of anxiety phenotype on the ratios of protective versus harmful chemokines (CTACK/CCL22) and cytokines ((IL-12+IFN-γ)/(IL-10 + IL-4))." (PMID 22558071, 2012). "Within this framework, the observed reduction in anxiety-related traits with higher serum concentrations of IL-10 in older dogs may not necessarily reflect maladaptive emotional disengagement or dysfunction." (PMID 40867746, 2025). "Nevertheless, anxiety was not correlated to IL-10 at any time point (all P>0.05)." (PMID 37878890, 2023). "Similarly, studies in animal models of MS (i.e., experimental autoimmune encephalomyelitis, EAE), have shown that IL-10 gene therapy has a beneficial effect on both motor and non-motor symptoms, including fatigue, anxiety and neuropathic pain." (PMID 36140159, 2022). "Thus, subjects with psychological stress-induced distress and anxiety showed significantly greater increases in IFNγ and lower IL-10 than those without distress and anxiety." (PMID 24228900, 2013). "In contrast, serum IL-10 levels were significantly reduced in GAD patients compared to HCs and showed a significant negative correlation with anxiety severity, implicating a potential link with the GAD pathophysiology." (PMID 38902708, 2024). "Subjects with psychological stress-induced distress and anxiety show significantly greater increases of interferon (IFN)-γ and decreases in IL-10 than those without such distress or anxiety." (PMID 35432030, 2022). "Interestingly, anxiety-/depressive-like behaviors of DEX-dam were restored with the normalization of P2ry12 and IL-10 after 10 weeks postpartum without antidepressants." (PMID 37396924, 2023).
ischemic stroke (112 papers, 2013 to 2026). A stroke disorder caused by obstruction of blood flow to the brain, due to thrombotic (local blood clot formation) or embolic (due to a blood clot or other material traveling from another site) event. "Lower levels of IL-10 are linked to poor functional outcomes in ischemic stroke patients, indicating that IL-10 is a significant prognostic factor." (PMID 40142325, 2025). "Different experimental models, both in vitro and in vivo, have proven that IL‐10 in ischemic strokes is associated with neuroprotective effects, apart from being an interesting and clinically useful diagnostic tool in TBI patients." (PMID 38332529, 2024). "Meanwhile, ischemia diminishes the release of anti-inflammatory substances, for instance IL-10, while enhancing inflammation, ultimately causing brain injury and neuronal demise following an ischemic stroke." (PMID 38273974, 2023). "One study showed that higher IL-10 levels were associated with poor outcomes in female patients with ischemic stroke, while another study reported that more elevated serum IL-10 was an independent prognosticator of ischemic stroke outcome." (PMID 34336007, 2021). "IL-10, an anti-inflammatory cytokine, is usually decreased in ischemic stroke patients and is inversely associated with stroke risk and with poor outcome." (PMID 33153204, 2020). "Recent studies have shown that the IL-10 gene polymorphism is associated with the incidence of ischemic stroke." (PMID 31701356, 2020). "Single nucleotide polymorphisms have been found in several genes related to inflammation and ischemic stroke; these polymorphisms include the following: IL-1β, IL-6, IL-10, MMP-2, MMP-9, MMP-12, E-selectin, L-selectin, CD36, PCSK9, and adiponectin." (PMID 33153204, 2020). "In vitro and in vivo models of ischemic stroke have convincingly directly and indirectly shown IL-10-mediated neuroprotection; although clinically, the role of IL-10 in predicting risk and outcomes is less clear." (PMID 28659854, 2017). "Decreased plasma levels of IL-10 were associated with increased neurological worsening in patients with ischemic stroke." (PMID 26491692, 2015). "Others have reported that reduced levels of IL-10 and low-producing IL-10 genotypes are associated with increased cIMT and that low-producing IL-10 genotypes are associated with coronary disease and ischemic stroke." (PMID 25948070, 2015). "We have shown that the addition of serum IL-10 and the SNPs score provides a significantly better prediction of ischemic stroke than conventional risk factors alone." (PMID 24040186, 2013). "Our results suggest that more prospective studies should be conducted to provide more data to justify the use of IL-10 and its SNPs as new biomarkers to identify an increased predisposition to ischemic stroke." (PMID 24040186, 2013). "We found IL10 to be associated with a 44% increase (OR 1.44; 95% CI 1.09–1.91) in the risk of overall ischemic stroke per copy of the risk allele of the IL 10 G1082A variant." (PMID 23505425, 2013). "Our results suggest that more prospective studies should be conducted to provide stronger evidence justifying the use of IL-10 and its SNPs as new biomarkers to identify a predisposition towards ischemic stroke." (PMID 24040186, 2013). "The lower serum IL-10 concentration and its selected genetic variations were significantly associated with an increased likelihood of ischemic stroke in this cross-sectional study." (PMID 24040186, 2013). "A high serum IL-10 (top tertile) was significantly associated with ischemic stroke (multivariable adjusted odds ratio (OR) =0.50; 95%CI 0.31-0.81)." (PMID 24040186, 2013). "Beyond the possible involvement of pro-inflammatory cytokines, lower concentrations of the anti-inflammatory cytokine IL-10 measured shortly after an ischemic stroke were associated with early neurological deterioration." (PMID 23675319, 2013).